IL6 (interleukin 6)
Diseases named in the same sentence as IL6 in open-access papers (continued):
Sharing a sentence is not in itself a finding about the gene and the disease.
leishmaniasis (continued). "Serum levels of the cytokines IL-10, IL-6, IL-12, and IFN-γ were increased in dogs with leishmaniasis." (PMID 41623056, 2026). "Regarding the pro-inflammatory cytokines IL-1β, IL-6, TNF-α, and IFN-y, only IL-1β increased in PBMC culture supernatants from dogs with leishmaniasis after transfection with the miR-194 inhibitor." (PMID 38241360, 2024). "Test for a possible regulatory role of miR-194 in the production of cytokines IL-1β, IL-6, IL-4, TNF-α, IFN-y, TGF-β, and IL-10, PBMCs from healthy dogs and those with leishmaniasis were transfected with miR-194 Mimic and Inhibitor." (PMID 38241360, 2024). "Previously, we have generated two models deciphering the dual action of IL6 in Leishmaniasis i.e., DSM depicting the anti-inflammatory role and HSM showing pro inflammatory role of IL6." (PMID 35011356, 2021). "The inflammatory cytokines such as interferon-γ, IL-1beta, IL-6, IL-8, and TNF-α are involved with leishmaniasis severity." (PMID 34735436, 2021). "This dual nature of IL-6 in leishmaniasis in the context of DNA methylation has not been deeply considered." (PMID 40396886, 2025). "IL-6 has been shown to either promote, suppress, or do not change the intracellular host defense to leishmaniasis." (PMID 31024534, 2019). "Besides, the chemokine MIP-1α (CCL3) is known to induce IL-1, IL-6, and TNF-α production with chemotactic and pro-inflammatory effects and acts as homeostasis promoter culminating in a Th1 response in the presence of receptors CCL3 and CCR5, fundamental in the control of leishmaniasis." (PMID 34253188, 2021). "We, however, did not examine the IL-6 level and concentrated on IL-10 but can hypothesize that IL-6 promotes the anti- inflammatory effect of IL-10 in leishmaniasis.The level of IFN-γ remained high, until the patients converted into symptomatic VL, and showed significantly low production." (PMID 32555598, 2020). "No changes were observed in the production of IL-6, TNF-α, or IFN-y in the PBMC culture supernatants of healthy dogs and those with leishmaniasis after transfection with miR-194 Mimic and Inhibitor." (PMID 38241360, 2024).
leptospirosis (33 papers, 2009 to 2025). A contagious bacterial infection caused by spirochetes of the genus Leptospira. "In conclusion, a high leptospiremia, pNGAL, and IL-6 level at baseline were associated with severe leptospirosis." (PMID 34272435, 2021). "From the univariable regression analysis, the factors associated with severe leptospirosis were leptospiremia, pNGAL, IL-6 levels at baseline (day 1)." (PMID 34272435, 2021). "In summary, our data demonstrated that a high leptospiremia, pNGAL, and IL-6 level at baseline were associated with severe leptospirosis." (PMID 34272435, 2021). "After adjusted the analysis of biomarkers by gender, age, and days of fever until enrollment, the multivariate regression analysis shown that high leptospiremia, pNGAL, and IL-6 levels at baseline (day 1) were factors associated with severe leptospirosis." (PMID 34272435, 2021). "Leptospirosis-susceptible hamsters showed strong expression of IL-1β, IL-6, TNF-α, and COX-2 in infected organs, whereas leptospirosis-resistant mice showed accelerated expression of the anti-inflammatory IL-10." (PMID 26824356, 2016). "IL-4, IL-6, IL-8, IL-10, IL-17A, and TNF-α levels in severe leptospirosis compared to mild disease, and an association between high IL-6, IL-8, IL-10 and fatal outcome." (PMID 26824356, 2016). "Among patients hospitalized with severe leptospirosis, increased concentrations of IL-6, IL-8, IL-10 and IFN-γ were associated with fatal outcomes in univariate analysis." (PMID 24069500, 2013). "Two of the cytokines, TNF-α and IL-6, are strongly associated with the severity of disease and the mortality of leptospirosis." (PMID 22870312, 2012). "As well soluble ST2, IL-6 and IL-8 levels were all associated with poor outcome in leptospirosis patients." (PMID 19488407, 2009). "Leptospirosis patients yielded elevated levels of IL-6 and IL-8 associated with mortality in the present study which were stronger than sST2." (PMID 19488407, 2009). "Consistent with our current findings, others and we have shown previously that high levels of proinflammatory cytokines, and their transcripts, IL-1α, IL-6, and IL-8 as well as the IL-1 antagonist receptor 1, are associated with poor disease outcomes for leptospirosis." (PMID 27812211, 2016). "In addition, the level of serum TNF-α was higher in leptospirosis patients with pulmonary hemorrhage, and serum IL-6 level was associated with fatalities from severe pulmonary hemorrhage syndrome." (PMID 26146835, 2015). "Cytokines, particularly TNF-α, IL-6, IL-1β and IL-10, have been found to be higher in severe and even fatal forms of human leptospirosis compared to milder infections." (PMID 40986630, 2025). "TNF-α, proinflammatory IL-6, chemokine IL-8, and anti-inflammatory IL-10 were known to play important roles in the pathogenesis of leptospirosis." (PMID 40861768, 2025). "A previous systematic review showed elevated levels of cytokines (IL-1β, IL-2, IL-4, IL-6, IL-8, IL-10, TNFα) in severe human leptospirosis compared with mild leptospirosis." (PMID 39729468, 2024). "TLR2 involvement during the pathogenesis response against leptospirosis was observed through the decrease of IL1β, TNFα, IL6, NFκB, and IL10 secretion/expression due to deficient/knocked down of the TLR2 receptors." (PMID 39729468, 2024). "Those suffering from severe leptospirosis exhibit indications of a ‘cytokine storm' characterised by elevated levels of IL-6, TNF-alpha and many other cytokines compared to those with milder symptoms." (PMID 39610672, 2024). "In patients with severe leptospirosis, elevated levels of IL-6, IL-10, and TNF-α have been observed during a cytokine storm." (PMID 38398036, 2024). "In studies of patients with multiple clinical manifestations with leptospirosis, the severity of the clinical picture has been associated with various serum cytokines levels, such as TNF-α, IL-10, and IL-6, but this conclusion remains controversial." (PMID 35203344, 2022).
leptospirosis (continued). "Especially, TNF-α and the interleukins IL-1β, IL-2, IL-4, IL-6, IL-8, and IL-10 were elevated in severe leptospirosis cases, whereas TNF-α, IL-6, IL-8, IL-10, interferon-γ, and soluble TNF receptor 1 were elevated in high fatality cases." (PMID 35237527, 2021). "Secondly, we measure pNGAL and IL-6 only on the first day of clinical suspicion of having leptospirosis." (PMID 34272435, 2021). "Nevertheless, results among the complicated leptospirosis showed elevated levels of IL-6 and TNF-α which shows a higher degree of pro-inflammatory action." (PMID 32264832, 2020). "High concentration of IL-6 is an indicator of septic shock and correlates to leptospirosis severity and SPHS." (PMID 29974037, 2018). "Immunological studies have evaluated the role of cytokines such as IFN-γ, IL-6 and IL-8 in leptospirosis." (PMID 25591623, 2015). "In univariate analysis, fatalities from SPHS had higher levels of IL-6, IL-8, and IL-10 in comparison to fatalities from other leptospirosis-related complications (P<0.05)." (PMID 24069500, 2013). "IL-6 was higher in patients who died from SPHS compared to those who died of other leptospirosis complications." (PMID 24069500, 2013). "We found that in patients with mild leptospirosis, there was some measurable elevation of pro-inflammatory cytokines, particularly IL-6 and IL-8." (PMID 24069500, 2013). "Patients that died from leptospirosis (n = 16) had significantly further elevated plasma levels on admission compared to the survivors, sST2 (p = .006), IL-6 (p = .003) and IL-8 (p = .003)." (PMID 19488407, 2009). "As well the odds of patients with leptospirosis dying increased by 3.2 (95%CI: 1.4–7.7, p = .008) with an AUC of 0.74 (p = .003), with a ten-fold increase of plasma IL-6 levels." (PMID 19488407, 2009). "Severe leptospirosis may trigger a cytokine storm, characterized by elevated serum levels of IL-6, IL-10, and TNF-alpha, indicating widespread dissemination of the pathogen." (PMID 38398036, 2024). "Our study also shows a correlation between serum IL-6 levels and severe leptospirosis." (PMID 34272435, 2021). "However, the present review found IL-1β to be low among leptospirosis patients, IL-6 to be elevated and TNF-α to be equivocal." (PMID 32264832, 2020). "This study shows that severe cases of leptospirosis are differentiated from mild disease by a “cytokine storm” process, and that IL-6 and IL-10 may play an immunopathogenic role in the development of life-threatening outcomes in human leptospirosis." (PMID 24069500, 2013). "The cytokine profile revealed that the levels of at least sixteen cytokines were significantly elevated in the leptospirosis patients’ sera, including the major proinflammatory factors IL-1β, IL-6 and TNF-α, and the major anti-inflammatory factors IL-4, IL-10 and IL-13." (PMID 22870312, 2012). "This high variability would also be limiting the value of IL-6 as a predictor in leptospirosis." (PMID 20076757, 2010). "Therefore, it is debatable whether IL-6 should be used as a predictor in the early diagnosis of human acute leptospirosis." (PMID 24130911, 2013). "Leptospirosis induces direct bacterial invasion of hepatocytes and triggers an inflammatory response by releasing inflammatory cytokines such as TNF- and IL-6." (PMID 39940058, 2025). "In patients with severe leptospirosis and pulmonary involvement, elevated levels of IL-6, CXCL8, and IL-10 were obtained when compared to patients with mild leptospirosis." (PMID 35203344, 2022). "Pro-inflammatory cytokines and enzymes which were IL-1β, IL-6, TNF-ɑ, IFN-γ and COX-2 and chemokines CXCL10/IP-10 and CCL3/MIP-α showed upregulation as reported in both human and animal leptospirosis." (PMID 35584087, 2022).
leptospirosis (continued). "In the present study, IL-6 was significantly high in the lung on day 1 p.i. and while in the kidney, it only appears on day 4 p.i. concurrent with the haemorrhagic presentation, thereby could support the role of this cytokine in the haemorrhagic presentation in leptospirosis." (PMID 35584087, 2022). "Significantly higher concentrations of IL-1β, IL-2, IL-4, IL-6, IL-8, IL-10, IL-17A, and TNF-α were found in sera of leptospirosis patients." (PMID 35927283, 2022). "Several earlier studies have identified significant expression of IL-1β, IL-2, IL-4, IL-6, IL-8, IL-10 and TNF-α in severe leptospirosis." (PMID 35584087, 2022). "Several host mediators have been investigated as potential biomarkers of leptospirosis, such as human serum (mannose binding lectin, MBL), interleukin 6 (IL-6), IL8, IL-10, soluble suppression of tumorigenicity 2 receptor, pentraxin 3, and copeptin." (PMID 35237527, 2021). "Fatal outcomes from Plasmodium falciparum malaria showed elevated levels of IL-6, IL-10 and TNF-α than in survival which was comparable to the results on leptospirosis." (PMID 32264832, 2020). "IL-1β, IL-6 and TNF-α were proposed to be pro-inflammatory cytokines which enhance the inflammatory response in leptospirosis." (PMID 32264832, 2020). "IL-1b, IL-2, IL-4, IL-6, IL-8, IL-10 and TNF-α levels were found to be significantly higher in severe than in mild leptospirosis." (PMID 32264832, 2020). "Several studies have demonstrated that the serum concentrations of IL-6 were significantly higher in severe leptospirosis patients than non-severe patients." (PMID 34272435, 2021). "Levels of IL-6 were measured in plasma from 32 leptospirosis participants (18 non-severe and 14 severe leptospirosis)." (PMID 33175842, 2020). "Similar to the present review, IL-6, IL-8, IL-10, IP-10, MCP-1, TNF-α and VEGF were found to be elevated in DHF, a condition common to almost all endemic settings for leptospirosis." (PMID 32264832, 2020). "Notably, although TNF and IL-6 cytokines were increased after antibiotic treatment of patients with leptospirosis, no secretion of IL-1ß was found in this study." (PMID 40986630, 2025). "Dysfunctional regulation of the levels of the cytokines/chemokines IL-6, IL-8, IL-10, IFN-ɣ, KC/GRO, MCP-1, MIP-1a, MIP-2 and TNF-α, after infection of C3H/HeJ mice with virulent Leptospira, were correlated to the severity of leptospirosis observed in this animal model." (PMID 39312584, 2024). "Notably, we observed the secretion/mRNA expression of several cytokines (IL6, IL8, IL-1β, TNFα, IFNγ, IL10, CCL2/MCP-1, CCL10, COX2, CXCL1/KC, CXCL2/MIP2) and immune effectors (hBD2, iNOS, Fibronectin, Oxygen, and Nitrogen reactive species) as key aspects of host TLR2 responses during leptospirosis." (PMID 39729468, 2024). "Previously, the association between long pentraxin PTX3, the protein that is in the same class as C-reactive protein, and mortality in severe leptospirosis was reported, where the serum PTX3 and IL-6 levels were higher in non-survivors." (PMID 33175842, 2020). "Serum levels of pro-inflammatory IL-6, chemokine IL-8 and anti-inflammatory IL-10 were significantly higher among patients that developed SPHS compared to non-SPHS leptospirosis patients." (PMID 29974037, 2018). "This total absence of inflammation in patients with leptospirosis was unexpected because of the elevated levels of CRP, considered as an inflammatory marker of leptospirosis and bacterial infections that correlate with IL-6." (PMID 40986630, 2025).
pulpitis (33 papers, 2012 to 2025). Inflammation of the dental pulp. "Earlier studies have also illustrated the effectiveness of miR-200c in mitigating inflammation by targeting IL-6 and IL-8 and downregulating NF-κB signaling, elucidating the mechanism(s) underlying the overexpression of miR-200c in inhibiting inflammation in pulpitis." (PMID 40724983, 2025). "In line with our study, IL6/JAK/STAT3 signaling pathway was found to be associated with pulpitis." (PMID 36593446, 2023). "And the successful detection of IL-6 and IL-8 upregulation has been recognized as a marker of the induction of pulpitis in numerous studies." (PMID 40001561, 2025). "IL-1β, TNF-α, and IL-6 are inflammatory mediators that have been widely reported to involve the inflammatory process and potentiate pain in pulpitis." (PMID 38627713, 2024). "A study of pulpitis has reported that quercetin reduces the production of pro-inflammatory cytokines IL-6 and IL-1722." (PMID 38902425, 2024). "The proinflammatory cytokines mentioned to be useful as a diagnostic tool in pulpitis and acute inflammation were IL-1 β, TNF-α, IL-6, and IL-8." (PMID 38893626, 2024). "To date, several studies have revealed the interactions between irreversible pulpitis and various inflammatory factors, such as the Toll-like receptors interleukin-8 (IL-8) and interleukin-6 (IL-6)." (PMID 37208635, 2023). "The expression levels of IL-6 and IL-8 were used to represent pulpal inflammation, since both cytokines have been shown to be potential biomarkers for irreversible pulpitis." (PMID 38071305, 2023). "Pulpitis is characterized by the production of high levels of pro-inflammatory cytokines including TNFα, IL-4, IL-6, IL-8, IL-10 and CXCL8." (PMID 35902880, 2022). "Studies have shown that inflammatory factors such as TNF-α, IL-6 and IL-8 are closely related to the development of pulpitis." (PMID 34154572, 2021). "IL-6 is upregulated in dentinal fluid of pulpitis, however, there is not significantly different between reversible and irreversible pulpitis." (PMID 38947881, 2021). "Dental pulps with pulpitis suffer higher expressions of proinflammatory cytokines (IL-1α, IL-1β, IL-6, and TNF-α) and innate immune response (TLR2, TLR4) than pulps without pulpitis." (PMID 31695620, 2019). "We therefore analyzed the expression levels of a Th1 cytokine (TNF-α) and a Th2 cytokine (IL-6) in the MMP-3 treated pulpitis tissues." (PMID 23285075, 2012). "IL-6 and IL-8 have been shown to be reliable biomarkers for diagnosis of irreversible pulpitis; however, the inability to discriminate between reversible and irreversible pulpitis is a major limitation." (PMID 38893654, 2024). "Gene expression profiles and bioinformatics analysis confirmed that M0 macrophages and neutrophils play an irreplaceable role in pulpitis immunity, and the critical genes in the immune reaction to pulpitis are suggested to be IL-6, TNF-α, IL-1β, CXCL8, and CCL2." (PMID 37179325, 2023). "In the pulpitis, LPS, TNFα and IL-6 are released at high levels." (PMID 35902880, 2022). "IL-10 acts as an anti-inflammatory cytokine that may be protective in terms of pulpitis development, decreasing IL-6 release, inhibiting Th1 and Th2 immune response, and thus, limits the intensity of inflammatory reaction." (PMID 33801317, 2021). "MMP‐3 promotes pulp regeneration in mild irreversible pulpitis by inhibiting IL‐6 activity." (PMID 34585454, 2021). "The IL-6 expression levels in the pulp tissues of the MMP-3-treated teeth were significantly reduced (35.52±9.08 pg/mg protein) at 3 days after sealing compared with the saline-treated teeth in the mild pulpitis model (78.95±10.09 pg/mg protein) (mean ± SEM)." (PMID 23285075, 2012). "In addition, TNFα and IL-6 are also highly expressed in the pulpitis." (PMID 35902880, 2022). "During the initiation of pulpitis, macrophages activate the immune response by phagocytosing pathogens and releasing inflammatory mediators such as TNF-α, IL-1β, and IL-6." (PMID 40001561, 2025).
pulpitis (continued). "Our results demonstrated IL-6, TNF-α TNF, IL-1β, CXCL8 and CCL2 are closely related to the immune infiltrating cells in pulpitis." (PMID 37179325, 2023). "LPS activates inflammatory cytokines, such as IL‐1, IL‐6, IL‐8, matrix metalloproteinase (MMP)‐9, MMP‐2, and TNF‐α28, 29, 30 in the pulpitis progress." (PMID 35334501, 2022). "Furthermore, in the rat pulpitis model, the HPCH/TA hydrogel displayed significantly reduced inflammatory cell infiltration and IL-6 expression compared to the control group." (PMID 39334895, 2024). "IL-6, TNF-α, IL-1, CXCL8, and CCL2 may be essential molecule of the immune response regulation network in pulpitis." (PMID 37179325, 2023). "In addition to investigating the possible regulatory mechanisms of DEGs, we screened key genes as biomarker candidates for the diagnosis of pulpitis, including PTPRC, CD86, CCL2, IL6, TLR8, MMP9, CXCL8 and ICAM1." (PMID 33046027, 2020). "Given the critical role of IL-6 in regulating the balance between the Treg and the Th17 cells, controlling IL-6 activities by MMP-3 is a potentially effective approach to treat not only mild irreversible pulpitis but also various chronic inflammatory diseases." (PMID 23285075, 2012). "Therefore, IL-6, TNF-α, IL-1β, CXCL8, and CCL2 may participate in the occurrence and development of pulpitis by regulating the corresponding immune cells, which needs further experimental verification." (PMID 37179325, 2023). "IL-6 was detected in inflamed pulp samples with reversible and irreversible inflammation, both in studies with and without differential diagnosis between the types of pulpitis." (PMID 34299403, 2021). "Furthermore, deciduous pulps with pulpitis suffered higher expressions of proinflammatory cytokines (IL-6 and MCP-1) and innate immune response (TLR1, TLR2, TLR3, TLR6, and TLR8) than pulps without pulpitis." (PMID 28377925, 2017). "The pulp tissues in the severe pulpitis model at 3 days after MMP-3 or saline-treated were already necrotic; we could not detect either IL-6 or TNF-α protein (data not shown)." (PMID 23285075, 2012).